ENSG00000280778 (novel protein, lncRNA-POLR3GL readthrough)
Gene: Protein-coding gene on chromosome 1 (145,927,258 to 145,977,811, forward strand). Ensembl gene ENSG00000280778.
Genetic constraint (gnomAD): Loss-of-function variants: 9 observed, 9.81 expected, observed/expected ratio (o/e) 0.92, 90% interval 0.55 to 1.58. That is too few expected variants to judge how well the gene tolerates losing a copy. Missense variants: 47 observed, 60.98 expected, observed/expected ratio (o/e) 0.77, 90% interval 0.61 to 0.98. Synonymous variants: 14 observed, 22.75 expected, observed/expected ratio (o/e) 0.62, 90% interval 0.41 to 0.96.